SOST (sclerostin)
Diseases named in the same sentence as SOST in open-access papers (continued):
Sharing a sentence is not in itself a finding about the gene and the disease.
osteoporosis (continued). "At present, PTH, PTHrP, and sclerostin antibodies for the treatment of osteoporosis are all protein drugs that have defects such as immunogenicity, easy degradation, high price, short half-life, and poor permeability." (PMID 37576993, 2023). "In adults, teriparatide and anti-sclerostin antibody have been used off-label in selected cases, demonstrating benefit in accelerating fracture healing and in concomitant treatment of osteoporosis." (PMID 37249457, 2023). "Some research have showed that SOST/sclerostin is involved in sclerosis, fracture repair, osteoporosis, and periprosthetic osteolysis." (PMID 37121919, 2023). "Anti-sclerostin antibodies (Scl-Ab), such as romosozumab and blosozumab, have been tested in osteoporosis treatment, revealing potent activity in stimulating bone formation and reducing bone resorption." (PMID 35328533, 2022). "Some studies on sclerostin and bone reported this condition and, in some cases, higher serum sclerostin was measured in women with normal BMD compared to women with osteoporosis." (PMID 35267956, 2022). "Studies on sclerostin will aid in the treatment and prevention of secondary osteoporosis in patients with SCI." (PMID 35742035, 2022). "Future pharmaceutical avenues include the humanised monoclonal antibody to sclerostin, Romosozumab, which is approved for the treatment of post-menopausal osteoporosis." (PMID 35795153, 2022). "Older adults with osteoporosis also have an acute increase in sclerostin in response to walking/resistance exercise." (PMID 36685192, 2022). "Due to a better understanding of the pathogenesis of osteoporosis, new treatments have been developed, such as anti-sclerostin, anti-DKK1 treatment, and analog of PTH-related protein." (PMID 35163300, 2022). "In postmenopausal Romanian women with osteoporosis, there is a close association between LRP5 and SOST polymorphisms." (PMID 35785219, 2022). "Pharmacologic inhibition of sclerostin enhances bone formation and shows positive outcomes in osteoporosis treatment." (PMID 35160258, 2022). "Beyond osteoporosis, sclerostin is involved in the pathogenesis of numerous other skeletal disorders." (PMID 35160258, 2022). "Artificial lowering of sclerostin levels in postmenopausal women with osteoporosis results in a reduction of bone resorption and increase in bone formation, eventually increasing BMD and thereby reducing fracture risk." (PMID 34448099, 2022). "Several monoclonal antibodies against sclerostin (Scl-Abs) had been developed as potential therapeutic agent for osteoporosis." (PMID 36456918, 2022). "Future research should focus on the use of sclerostin as biomarker for osteoporosis in fracture patients." (PMID 35705746, 2022). "The monoclonal antibody against sclerostin has been approved as a novel treatment method for osteoporosis." (PMID 35562828, 2022). "Romosozumab is an antibody that targets sclerostin and is useful for treating osteoporosis, especially in elderly women with severe osteoporosis." (PMID 35962437, 2022). "This study aims to directly examine the osteoclast and sclerostin expression in osteocytes in the femoral head removed during surgery to determine the cellular activity that can induce osteoporosis in the femoral head following risedronate treatment." (PMID 36363523, 2022). "A limited number of studies investigated the relation between osteoporosis and sclerostin levels and found divergent results." (PMID 35705746, 2022). "In humans, the administration of anti-sclerostin antibody, romosozumab, to patients with osteoporosis markedly increased bone formation and bone mass but there has been no report that demonstrated an effect of romosozumab in improving obesity." (PMID 36424386, 2022). "Nevertheless, further studies are warranted on the relationship and related mechanisms of osteoclast activity and sclerostin activity in bone during osteoporosis." (PMID 36363523, 2022).
osteoporosis (continued). "Since then, a large number of studies have reported the roles of Wnt ligands and Wnt inhibitors in bone metabolism in addition to the successful application of sclerostin antibodies to the treatment of osteoporosis." (PMID 35563281, 2022). "Considering its role in bone homeostasis, targeting sclerostin with the antisclerostin antibody was evidenced as an effective treatment of osteoporosis." (PMID 35160258, 2022). "Sclerostin has already become the target of a new drug for osteoporosis and currently anti-sclerostin monoclonal antibody is used to treat severe osteoporosis." (PMID 35216490, 2022). "Recently, many studies have been conducted on the role of sclerostin and Wnt signaling in the treatment of osteoporosis." (PMID 36363523, 2022). "Hyperthyroidism induces the expression of sclerostin, subsequently leading to osteoporosis, but a dramatic decline in serum sclerostin occurs after treatment with drugs." (PMID 35464058, 2022). "Sclerostin (SOST) is an endogenous inhibitor of bone formation, and an attractive target for treatment of osteoporosis." (PMID 36581888, 2022). "Functionally, SOST acts as an inhibitor of bone formation, making it a therapeutic target for the treatment of osteoporosis." (PMID 36581888, 2022). "The sclerostin monoclonal antibody romosozumab is now approved for treatment of osteoporosis in the US, Japan, Canada, Australia, and South Korea)." (PMID 34502021, 2021). "Sclerostin, secreted by osteocytes, is an inhibitor of the Wnt/β–catenin bone metabolic pathway, and is involved in osteoporosis and metabolic disease." (PMID 34572220, 2021). "A good example of the latest is the recently, FDA approved humanized anti-sclerostin monoclonal antibody Romosozumab (Amgen, Thousand Oaks, CA, USA), used for the treatment of osteoporosis." (PMID 34452242, 2021). "Together, these discoveries provide key insights into the unexpected, rapid regulation of osteocyte sclerostin protein by the lysosome and reveal new therapeutic targets that can be exploited to improve bone mass in conditions such as osteoporosis." (PMID 33779549, 2021). "As a relatively new drug for osteoporosis, romosozumab, a humanized monoclonal antibody that binds and inhibits sclerostin, has been prescribed." (PMID 34071733, 2021). "Romosozumab is a monoclonal antibody against sclerostin, and is approved for the treatment of osteoporosis to improve BMD." (PMID 34501423, 2021). "Romosozumab, for example, is a sclerostin inhibitor recently approved for treatment of post-menopausal osteoporosis and this drug can promote bone formation and inhibit bone resorption." (PMID 34036041, 2021). "Potential small-molecule drug candidates obtained in this study are expected to provide new therapeutics for osteoporosis as well as insights into the structure–activity relationship of sclerostin inhibitors for rational drug design." (PMID 34361085, 2021). "The hindlimb unloading model has also contributed to identify potential drug candidates (e.g., Sclerostin antagonism using monoclonal antibodies) for the treatment of conditions such as osteopenia and osteoporosis." (PMID 34737712, 2021). "A humanized monoclonal antibody against sclerostin, termed romosozumab (brand name EVENITY®), has been approved in the U.S. for women with osteoporosis after menopause at a high risk for fracture." (PMID 34502021, 2021). "Sclerostin antibody (romosozumab) was recently approved for clinical use in the United States to treat osteoporosis." (PMID 33977198, 2021). "Accordingly, regulating sclerostin bioavailability has tremendous therapeutic potential for conditions of low bone mass, such as osteoporosis." (PMID 33779549, 2021). "In fact, several molecules involved in the regulation of Wnt signaling, such as sclerostin, are currently being targeted in bone-building therapies for patients with osteoporosis." (PMID 34452242, 2021).
osteoporosis (continued). "The understanding of these pathways through the study of rare bone diseases has led to the development of specific therapeutics agents such as denosumab and anti-sclerostin antibodies for the treatment of common osteoporosis." (PMID 33435159, 2021). "The limitation of the Sclerostin action within the skeleton makes it a good candidate for osteoporosis, with fewer concerns of systemic effects." (PMID 33805567, 2021). "In fact, it has been reported that HBOT increases the osteogenic differentiation of mesenchymal stem cells in vitro, whereas in an animal model, HBOT appeared to protect from the osteoporosis induced by hind limb unloading through decreased SOST expression." (PMID 34946440, 2021). "Second, sclerostin inhibits bone formation and may cause osteoporosis; therefore, it may be necessary to shorten the duration of treatment by combining other anticancer drugs, choose selective arterial injection to allow sclerostin to be locally effective, and combine bone resorption inhibitors." (PMID 34885123, 2021). "Prior studies in laying hens demonstrated that mRNA level of SOST can be a good predictive biomarker for bone quality variation, such as in osteoporosis, and SOST can decrease bone formation by reducing osteoblastic activity." (PMID 33816591, 2021). "Lessons learned from these forms of osteopetrosis have led to the development of the anti-sclerostin monoclonal antibodies to treat osteoporosis." (PMID 33435159, 2021). "In vivo studies assessing sclerostin as a therapeutic target for bone disease receive significant attention in the osteoporosis field." (PMID 34501423, 2021). "Trials have been conducted in adult osteoporosis, which led to the market approval of antibody therapy against sclerostin, an inhibitor of the WNT signaling pathway." (PMID 33435159, 2021). "Vascular sclerostin might also drive the calcification paradox: sclerostin-producing transdifferentiated vascular SMCs possibly cause a sclerostin spillover into the circulation, thus contributing to the downregulation of bone formation and promoting osteoporosis." (PMID 33923139, 2021). "This antibody-mediated blockade of sclerostin has been used in many clinical trials for osteoporosis." (PMID 34885123, 2021). "There are, however, some indirectly targeting antibody-based treatments to osteocyte-secreted molecules such as the recently FDA-approved sclerostin monoclonal antibody treatment for osteoporosis, promoting bone formation." (PMID 35265628, 2021). "The understanding of the wingless-type mouse mammary tumor virus integration site (Wnt) signaling pathway in bone metabolism identified the negative regulator of bone mass sclerostin as a potential target for the treatment of osteoporosis." (PMID 31858345, 2020). "The therapeutic potential of targeting sclerostin has recently been exploited as an anabolic treatment for osteoporosis." (PMID 31894854, 2020). "Recently, several studies have found that the sclerostin antibody has clinical implications for the treatment of osteoporosis." (PMID 32493422, 2020). "Sclerostin (SOST) is an osteocyte-derived glycoprotein that is known as a Wnt inhibitor and it is highly involved in osteoporosis." (PMID 32443915, 2020). "The meticulous research on the molecular mechanism of osteocytic sclerostin on bone remodeling led to the development of anti-sclerostin antibodies to treat osteoporosis and other skeletal disorders demanding an increase in bone mass." (PMID 32733380, 2020). "Anti-resorptive agents such as bisphosphonates, selective estrogen receptor modulators (SERMs), and anabolic drugs that stimulate bone formation, including PTH analogs and sclerostin inhibitors, are current treatments for osteoporosis." (PMID 32582688, 2020). "A humanized monoclonal antibody to sclerostin has been clinically tested to prevent or treat the bone fracture and/or osteoporosis through the promotion of Wnt/β-catenin signaling." (PMID 33159018, 2020).
osteoporosis (continued). "This suggests a local upregulation of the action of sclerostin on arterial remodeling, which is of particular importance as the anti-sclerostin antibodies with prolonged pharmacokinetic release are being developed for the treatment of osteoporosis." (PMID 32095286, 2020). "This review aims to outline the role of sclerostin, the efficacy and safety of anti-sclerostin therapies and in particular romosozumab and their place in therapeutic strategies against osteoporosis or other bone diseases." (PMID 33114755, 2020). "Scientists have developed a humanized monoclonal antibody directed against sclerostin (romosozumab), which is approved for the treatment of osteoporosis." (PMID 32947946, 2020). "Regarding osteoporosis, several TGF-β superfamily members (TGFB1, BMP2, BMP4, and Sclerostin) have been implicated as candidate genes in osteoporosis." (PMID 33297501, 2020). "A study on the genetics and pathophysiology of sclerosteosis and van Buchem disease led to the discovery of sclerostin and its function that contributed to the development of an anti-sclerostin drug to treat osteoporosis." (PMID 32733380, 2020). "Romosozumab is an anti-sclerostin antibody, which has recently been developed as anabolic treatment for osteoporosis, and is now widely available." (PMID 33658983, 2020). "Anti-sclerostin monoclonal antibody has the potency to treat diseases with low bone mass phenotype, including osteoporosis." (PMID 32733380, 2020). "The discovery that sclerostin is the defective protein underlying the rare heritable bone mass disorder, sclerosteosis, ultimately led to development of anti-sclerostin antibodies as a new treatment for osteoporosis." (PMID 33658983, 2020). "In AS, the low expression of SOST is considered as an important biomarker of AS progression, and its mechanism is similar to osteoporosis." (PMID 32793634, 2020). "Studies of patients with rare bone diseases and the understanding of the Wnt signaling pathway in bone metabolism identified the negative regulator of bone mass sclerostin as a potential target for the treatment of osteoporosis." (PMID 31858345, 2020). "The sclerostin monoclonal antibody (Scl-Ab/ Romosozumab), which inhibits the function of sclerostin and enhances bone formation (anabolic compound), is the most recent addition to the osteoporosis set of medications." (PMID 33162933, 2020). "The higher sclerostin serum levels found in these patients compared to the controls suggest that sclerostin is involved in disuse osteoporosis in humans, potentially via the Wnt/beta-catenin signaling inhibition." (PMID 32456199, 2020). "The aim of this study is to investigate the involvement of CpG methylation in regulation of SOST expression in patients with primary osteoporosis." (PMID 30729116, 2019). "Currently, a wave of new sclerostin-targeting therapies are being explored in an effort to control sclerostin’s antianabolic properties in the treatment of osteoporosis and other skeletal disorders." (PMID 30707688, 2019). "Nevertheless, little is known about the specific relationship between DNA methylation and SOST gene expression in patients with primary osteoporosis." (PMID 30729116, 2019). "Sclerostin antibody recently gained approval for clinical use to treat osteoporosis, but the biology surrounding sclerostin antagonism is still incompletely understood." (PMID 31505764, 2019). "As a potential therapeutic agent in osteoporosis and thus, also impaired bone healing, application of a sclerostin neutralizing antibody has also been shown to enhance metaphyseal bone healing in rats." (PMID 31752267, 2019). "Results were similar to those observed in patients with osteoporosis treated with anti-sclerostin therapy." (PMID 31888683, 2019). "The treatment of osteoporosis by using anti‐sclerostin antibodies has recently been an important research topic, scFvs have significant advantages due to its high affinity and minimal antigenicity." (PMID 31012249, 2019).
osteoporosis (continued). "Romosozumab (AMG785: a humanized monoclonal anti-sclerostin antibody) has been clinically evaluated and was recently approved for clinical treatment of osteoporosis." (PMID 31137666, 2019). "The recently approved anabolic osteoporosis treatment romosozumab, a sclerostin neutralizing antibody, was developed with knowledge gained from subjects with osteosclerosis resulting from SOST gene mutations." (PMID 32117046, 2019). "Implant osseointegration is superior in the SOST knockout mice suggesting that SOST is a promising target to enhance implant osseointegration in osteoporosis." (PMID 31031968, 2019). "Romosozumab, an antibody against SOST, is a promising new therapeutic agent against osteoporosis, improving bone formation, and microarchitecture." (PMID 31451913, 2019). "Strategies to neutralize sclerostin, for instance with clinically tested romosozumab, an anti-sclerostin antibody, hold promise for treatment of osteoporosis." (PMID 30924022, 2019). "They led to the development of anti-sclerostin therapies for osteoporosis and other low bone mass disorders." (PMID 31888683, 2019). "So, it is very interesting and necessary to provide more evidences to demonstrate the expression of sclerostin in osteoporosis and its correlation with DNA methylation." (PMID 30729116, 2019). "An antibody that targets sclerostin (romosozumab) has already passed phase III clinical trials for the treatment of osteoporosis and is expected to become a new therapeutic." (PMID 31088250, 2019). "Since anti-sclerostin antibody treatment demonstrates bone mass increase, targeting ligands that are secreted by osteocytes probably affects the fate of consequent osteoporosis and mineral disturbance in CKD." (PMID 31027235, 2019). "Nowadays, anti-sclerostin antibodies are being tested to treat severe osteoporosis in clinical trials." (PMID 30729116, 2019). "Monoclonal antibodies directed to inhibiting sclerostin and cathepsin K inhibitors have been generated for the treatment of osteoporosis." (PMID 31281368, 2019). "Subsequent studies have indicated that monoclonal antibodies to sclerostin such as romosozumab have been used in preclinical and clinical studies of osteoporosis with beneficial outcomes for bone mass and microstructure, and fractures risk reduction." (PMID 30949129, 2019). "To date, only anti-sclerostin antibodies against osteoporosis have been clinically used as molecular-targeted agents for Wnt-related molecules." (PMID 31698687, 2019). "A report shows that the administration of selective estrogen receptor modulators (SERM), used in the treatment of osteoporosis, significantly decreases serum sclerostin level." (PMID 31698687, 2019). "Sclerostin is now recognized as a new target for the treatment of patients with osteoporosis and other skeletal disorders." (PMID 30949129, 2019). "IL-20 and sclerostin are positively correlated in the serum of bone fracture, osteopenia, and osteoporosis patients." (PMID 29690863, 2018). "In fact, these observations provided the foundation for the development of romosozumab, an anti-sclerostin antibody, which has shown promising results in a Phase 3 trial to treat osteoporosis." (PMID 29844946, 2018). "In an animal model of osteoporosis, NMP prevented the estrogen deficiency-induced increased expression of sclerostin." (PMID 30366476, 2018). "Our objective has been to study in detail the allelic architecture of three Wnt pathway genes: WNT16, DKK1 and SOST, in the context of osteoporosis." (PMID 30026596, 2018). "Monoclonal antibody anti-sclerostin, Romosozumab, has been developed and tested in clinical trials in patients with osteoporosis." (PMID 30410490, 2018). "Sclerostin is commonly referred to as an osteocyte-specific protein and clinically focused as an emerging therapeutic target for treating osteoporosis and osteoporotic fracture." (PMID 30071108, 2018).